ENDOU (endonuclease, poly(U) specific)
Description:
Endoribonuclease that cleaves single-stranded RNAs at 5' of uridylates and releases a product with a 2',3'-cyclic phosphate at the 3'-end. The UU and GU sites are more efficiently cleaved than CU and AU sites. Targets mRNAs to regulate their expression.
Synonyms: PP11; P11; PRSS26
Tractability: Antibody: UniProt places it where antibodies can reach, with high confidence; its Gene Ontology location is reachable by antibodies, with high confidence; UniProt predicts a signal peptide or a membrane-spanning region. PROTAC: ubiquitination databases record sites on it.
Gene: Protein-coding gene on chromosome 12 (47,709,734 to 47,725,567, reverse strand). Ensembl gene ENSG00000111405.
Subcellular location: Secreted
Gene Ontology:
Molecular function: RNA binding; RNA endonuclease activity; serine-type peptidase activity; growth factor activity; manganese ion binding; polysaccharide binding; RNA nuclease activity; scavenger receptor activity
Biological process: female pregnancy; negative regulation of lipid catabolic process; post-transcriptional gene silencing; proteolysis; immune response; signal transduction; vesicle-mediated transport
Cellular component: cytoplasm; extracellular region; plasma membrane
Genetic constraint (gnomAD): Loss-of-function variants: 41 observed, 48.61 expected, observed/expected ratio (o/e) 0.84, 90% interval 0.66 to 1.09. The upper end of that interval is the gene's LOEUF score, 1.09, which puts it in group 4 of 6, group 1 being the genes least tolerant of losing a copy. Missense variants: 441 observed, 505.97 expected, observed/expected ratio (o/e) 0.87, 90% interval 0.81 to 0.94. Synonymous variants: 167 observed, 190.18 expected, observed/expected ratio (o/e) 0.88, 90% interval 0.77 to 1.
Homologues: Orthologues: chimpanzee ENDOU (99% identical), macaque ENDOU (97% identical), pig ENDOU (86% identical), dog ENDOU (83% identical), guinea pig ENDOU (82% identical), mouse Endou (82% identical), rat Endou (80% identical), rabbit ENDOU (71% identical), tropical clawed frog endou (54% identical), zebrafish endou (38% identical), Drosophila melanogaster CG2145 (27% identical), Caenorhabditis elegans endu-1 (23% identical), and 2 more.
Diseases named in the same sentence as ENDOU in open-access papers:
ENDOU is named in the same sentence as 14 diseases in open-access papers, as found by Europe PMC text mining. Sharing a sentence is not in itself a finding about the gene and the disease. The quoted sentences say what the papers report.
virus infection (3 papers, 2017 to 2025). "Furthermore, compared to wild-type virus infection, EndoU-deficient virus infection resulted in increased cytosolic dsRNA or yielded more dsRNA that did not localize with the viral RTC during the early phase, thus activating host cell dsRNA sensors, such as Mda5, PKR and OAS." (PMID 38634805, 2024). "Collectively, these results demonstrate that cytosolic dsRNA is increased in EndoU-mutant virus infection and suggest that elevated dsRNA is the trigger for the activation of Mda5, PKR, and OAS." (PMID 28158275, 2017). "This suggests that early during EndoU-deficient virus infection, viral dsRNA intermediates are released to the DMV exterior and detected by cytosolic dsRNA sensors, whereas in wild-type virus infection, nsp15 prevents this from happening using its EndoU activity." (PMID 38634805, 2024). "Current literature has documented that the conserved Nsp15/EndoU activity of CoVs is not directly involved in viral RNA synthesis but rather mediates the evasion of host antiviral responses, thereby promoting viral infection." (PMID 40838727, 2025).
breast carcinoma (2 papers, 2020 to 2022). "ENDOU (PP11) was detected in 66.7% of analyzed mucinous cystadenocarcinomas, 57.1% of serous cystadenocarcinomas, but not in normal ovaries, 47% of breast cancers and 38% of all testicular and gastric cancers." (PMID 36531250, 2022).
acne (1 paper, 2025). An inflammatory process of the sebaceous glands which is characterized by comedones, nodules, papules and/or pustules on the skin. "For example, cystatin E/M (CST6), endonuclease, poly(U) specific (ENDOU), and galanin (GAL) were associated with acne in our study (e.g. galanin: beta = 0.27 s.d." (PMID 41068475, 2025).
asthma (1 paper, 2024). "With respect to increased risk of asthma, blood genes again had the largest relative effect sizes in males (BAG6, CCNG, CRAT, PTPA, and FAM89B), with female training genes exhibiting the largest effects in ATP6V1G2 in the vastus lateralis, ENDOU in white adipose, and CCNF in blood." (PMID 38693125, 2024).
infection (7 papers, 2017 to 2026). The state of being infected such as from the introduction of a foreign agent such as serum, vaccine, antigenic substance or organism. "Further immunofluorescence analysis revealed that rH234A infection resulted in approximately threefold more cells exhibiting PABPC1 nuclear accumulation—a hallmark of RNase L activation—supporting the idea that Nsp15/EndoU antagonizes this pathway." (PMID 40838727, 2025). "However, infection with EndoU activity-deficiency mutant virus rIBV-nsp15-H238A results in the accumulation of viral dsRNA, triggering a PKR-eIF2α-dependent shutdown of protein synthesis and leading to the nuclear relocation of PABPC1." (PMID 40096172, 2025). "Future studies could assess the effects of NSC95397 with late infection conditions, in appropriate human immune cells or in mouse models, which are sensitive to mutations of nsp15 EndoU activity." (PMID 34198324, 2021). "Infection with a recombinant 229E expressing an inactivated nsp15 endoribonuclease U (EndoU) led to increased dsRNA levels, stronger induction of all three antiviral pathways, and attenuation of replication relative to wild-type 229E." (PMID 41369222, 2026). "Notable among these is the conserved nsp15 endoribonuclease (EndoU), which has previously been shown to act as an innate immune antagonist during infection with all four coronavirus genera (alpha, beta, gamma, and deltacoronaviruses) (27, –, 36)." (PMID 41369222, 2026). "Growth kinetic assays revealed that both viruses exhibited comparable replication kinetics in Vero-AT cells at two different multiplicities of infection (MOIs), 0.0001 and 0.01, indicating a dispensable role of the EndoU activity in SARS-CoV-2 replication." (PMID 40838727, 2025). "Finally, we show that MHVH277A replication is associated with increased dsRNA levels during the early phase of the infection, providing a likely PAMP for the observed simultaneous activation of multiple cytoplasmic dsRNA-sensors in cells infected with EndoU-deficient coronaviruses." (PMID 28158275, 2017). "We showed that inactivation of EndoU in PEDV results in an increased type I and type III IFN response during infection." (PMID 32198201, 2020).
tumor (2 papers, 2020 to 2022). "The markers of M2 macrophages (CD163, VSIG4, and MS4A4A) all showed significant negative correlation coefficient with ENDOU, implicating potential role of ENDOU in tumor infiltrating M2 macrophages." (PMID 33614471, 2020). "We validated the mRNA expression levels of the 4 ferroptosis-related genes (ZNF566, TMEM150C, ENDOU, MALSU1) in the tumor tissue and adjacent tissue of 10 HNSCC patients by RT-qPCR." (PMID 36531250, 2022). "In most validated samples ZNF566, TMEM150C, ENDOU were all significantly decrease in tumor tissues than in normal tissues." (PMID 36531250, 2022). "In this study, we found ENDOU negative correlates with tumor infiltrating neutrophils, dendritic cells and macrophages, especially M2 macrophages." (PMID 33614471, 2020). "Based on the founding that tumor suppressor gene ENDOU was negatively correlated with M2 markers of CD163, VSIG4, and MS4A4A, we speculated that ENDOU may also inhibit macrophages M2 polarization in tumor microenvironment." (PMID 33614471, 2020). "It was the first time that ENDOU was identified as a tumor suppressor, with prognostic significance and negative correlation with tumor infiltrating M2 macrophages." (PMID 33614471, 2020).
ENDOU also shares sentences with these, for which no sentence is quoted: cancer (2 papers); Anxiety (1); bladder cancer (1); COVID-19 (1); gastric cancer (1); liver cancer (1); mucinous cystadenocarcinoma (1); serous cystadenocarcinoma (1).